DNER (delta/notch like EGF repeat containing)
Description:
Activator of the NOTCH1 pathway. May mediate neuron-glia interaction during astrocytogenesis (By similarity).
Synonyms: BET; UNQ26
Tractability: Antibody: its Gene Ontology location is reachable by antibodies, with high confidence; UniProt places it where antibodies can reach, with medium confidence; UniProt predicts a signal peptide or a membrane-spanning region. PROTAC: ubiquitination databases record sites on it; a small molecule that binds it is known.
Gene: Protein-coding gene on chromosome 2 (229,357,629 to 229,714,581, reverse strand). Ensembl gene ENSG00000187957.
Subcellular location: Cell membrane
Pathways (Reactome):
Signal Transduction: Activated NOTCH1 Transmits Signal to the Nucleus
Gene Ontology:
Molecular function: protein binding; calcium ion binding; clathrin binding; Notch binding; transmembrane signaling receptor activity
Biological process: central nervous system development; endocytosis; neuron migration; synapse assembly; nervous system development
Cellular component: dendrite; early endosome; plasma membrane; neuronal cell body
Genetic constraint (gnomAD): Loss-of-function variants: 30 observed, 72.49 expected, observed/expected ratio (o/e) 0.41, 90% interval 0.31 to 0.56. The upper end of that interval is the gene's LOEUF score, 0.56, which puts it in group 2 of 6, group 1 being the genes least tolerant of losing a copy. Missense variants: 913 observed, 944.36 expected, observed/expected ratio (o/e) 0.97, 90% interval 0.92 to 1.02. Synonymous variants: 414 observed, 373.85 expected, observed/expected ratio (o/e) 1.11, 90% interval 1.02 to 1.2.
Homologues: Orthologues: chimpanzee DNER (99% identical), macaque DNER (98% identical), dog DNER (92% identical), rat Dner (91% identical), pig DNER (91% identical), mouse Dner (90% identical), rabbit DNER (88% identical), guinea pig DNER (82% identical), tropical clawed frog dner (64% identical), zebrafish dner (55% identical), Caenorhabditis elegans F55H12.3 (25% identical), Drosophila melanogaster Ser (22% identical), and 3 more. Paralogues in human: JAG2 (24% identical), JAG1 (24% identical), NOTCH4 (23% identical), DLL1 (22% identical), DLL4 (21% identical).
Diseases named in the same sentence as DNER in open-access papers:
DNER is named in the same sentence as 37 diseases in open-access papers, as found by Europe PMC text mining. Sharing a sentence is not in itself a finding about the gene and the disease. The quoted sentences say what the papers report.
breast carcinoma (7 papers, 2021 to 2023). "Taken together, DNER clearly plays a critical role in the progression of cancer and patient prognosis, at least in gastric cancer, breast cancer, prostate cancer, and hepatocellular carcinoma." (PMID 37373228, 2023). "A subacute, progressive ataxic syndrome in the proper clinical context should therefore raise suspicion for a PNS related to Hodgkin lymphoma (anti-DNER), breast cancer (anti-Ri/ANNA-2), testicular cancer (anti-KLHL11), or others." (PMID 37239077, 2023). "On the other hand, genes such as DNER affect breast cancer metastasis more directly through the activation of the EMT program." (PMID 35614362, 2022). "Among the genes that were most significantly upregulated were some that have been previously identified as drivers of breast cancer metastasis, e.g. CSF 3, G0S 2, COL7A 1, IL1 6, and DNER." (PMID 35614362, 2022). "Delta/Notch-like EGF repeat containing (DNER) is a transmembrane protein that regulates EMT to enhance the proliferation and metastasis of breast cancer cells via the Wnt/β-catenin pathway." (PMID 34604089, 2021). "The expression of key markers associated with proliferation (MKI67, PCNA, CCNB1, MYBL2, BUB1, CCND1), apoptosis (BCL2, CASP7, CASP8, CASP9, CASP3, BAX, APAF1), differentiation (CDH1, CD24, EPCAM, ESR1, NGFR, RUNX1), and breast cancer stemness (CD44, ITGA6, DNER, ALDH1A3, ABCG2, PROCR) was assessed." (PMID 35183258, 2022).
gastric cancer (3 papers, 2023 to 2025). A primary or metastatic malignant neoplasm involving the stomach. "DNER is an inflammation‐associated membrane protein expressed mainly in the cerebellum, pituitary gland, and adrenal glands; it has been shown to be a potential therapeutic target for gastric cancer and osteoarthritis in previous studies." (PMID 40552337, 2025). "Overexpression of NICD increased DNER expression in the gastric cancer cells, suggesting a positive feedback regulation of Notch signaling." (PMID 37373228, 2023). "This study aimed to investigate the oncogenic role of DNER and the mechanisms behind its oncogenic role in gastric cancer." (PMID 37373228, 2023). "Inhibition of TGF-β signaling significantly interfered not only with the spheroid formation of the gastric cancer cells, but also with the upregulation of DNER in the spheroid-cultured cells." (PMID 37373228, 2023). "This study provides evidence for the critical role of DNER in regulating spheroid formation, cell proliferation, and survival of gastric cancer cells." (PMID 37373228, 2023). "Taken together, DNER regulates cell proliferation, survival, and invasive capacity of the gastric cancer cells through the activation of Notch signaling, which may facilitate tumor progression into an advanced stage." (PMID 37373228, 2023). "The role of DNER in the maintenance of gastric cancer stem cells, and potential mechanisms involved in the regulation of proliferation and survival of gastric cancer cells was investigated by tumor spheroid cultures and analysis of the expression of the associated genes." (PMID 37373228, 2023). "The study identified a panel of four mRNAs (AGTR1, DNER, EPHA7, and SUSD5) significantly upregulated in recurrent gastric cancer tissues compared to non‐recurrent tissues." (PMID 39556695, 2024). "DNER, which was upregulated through the activation of TGF-β signaling, is supposed to modulate the spheroid-forming capacity by regulating cell proliferation and the survival of gastric cancer cells." (PMID 37373228, 2023).
diabetes (2 papers, 2021 to 2023). "We anticipate that the mechanisms we have defined in this study will provide a foundation for future studies to fully elucidate the role of DNER in the healthy pancreas, and to assess whether DNER mutations or polymorphisms contribute to diabetes risk." (PMID 37223028, 2023).
prostate carcinoma (2 papers, 2023 to 2024). A carcinoma that arises from epithelial cells of the prostate gland. "Upregulation of the expression of Delta/notch-like epidermal growth factor-related receptor (DNER) and its oncogenic role have been reported in several cancers, including gastric, breast, and prostate cancers." (PMID 37373228, 2023). "Furthermore, DNER has been reported to be upregulated in various cancer tissues, such as breast and prostate cancer tissues." (PMID 37373228, 2023). "DNER, a neuron-specific transmembrane protein with extracellular EGF-like repeats, has been demonstrated to facilitate prostate cancer advancement and enhance PC-3 cell proliferation by modulating the core genes associated with cancer stem cells." (PMID 38742115, 2024).
autism spectrum disorder (1 paper, 2020). A spectrum of developmental disorders that includes autism, and Asperger syndrome. "In addition, a significant enrichment among the nominal DEGs for genes implicated in autism spectrum disorder (ASD) was found (e.g., AFF2, DNER, DPP6, DPP10, RELN, CACNA1C), as well as several that are strong candidate genes for the development of eye problems found in LS, including glaucoma." (PMID 32393163, 2020).
cardiac hypertrophy (1 paper, 2018). "The role if any played by DNER, REG3A, and IRX1 to diastolic dysfunction and cardiac hypertrophy is not reported, although genetic variants of the IRX1 gene were recently reported to contribute to the pathogenesis of congenital heart disease." (PMID 29556499, 2018).
dementia (1 paper, 2017). Loss of intellectual abilities interfering with an individual's social and occupational functions. "The specific implication of Jagged1 in Notch-dependent functions is emphasized by the evidence that the other Notch ligand, DNER, which is also expressed in hippocampal neurons, remains virtually unchanged with the progression of dementia." (PMID 28848392, 2017).
glioma (1 paper, 2025). A benign or malignant brain and spinal cord tumor that arises from glial cells (astrocytes, oligodendrocytes, ependymal cells). "DNER, a noncanonical Notch ligand, was found to suppress glioma growth by inhibiting the oncogene TOR4A and hindered the growth and induced differentiation of GBM-derived neurospheres." (PMID 39874307, 2025).
Hodgkins lymphoma (1 paper, 2023). A heterogeneous group of malignant lymphoid neoplasms of B-cell origin characterized histologically by the presence of Hodgkin and Reed-Sternberg (HRS) cells in the vast majority of cases. "Tr/delta/notch-like epidermal growth factor-related receptor (DNER) is another “high-risk” antibody with >90% association with cancer, typically Hodgkin lymphoma." (PMID 37239077, 2023).
nasopharyngeal carcinoma (1 paper, 2020). A carcinoma arising from the nasopharyngeal epithelium. "In addition, DNER acts as a ligand for Notch1, activating the Notch signalling pathway, and the knockdown of Notch1 expression can inhibit the migration and invasion of nasopharyngeal carcinoma cells by reversing EMT32." (PMID 32811806, 2020).
neuroblastoma (1 paper, 2014). Neuroblastoma (NB) is the most common solid, extracranial childhood tumor. "In line with previously published analyses of HOXC9 in neuroblastoma cells, we found a significant up-regulation of genes involved in neuronal differentiation pathways such as DNER, NEFL, DBH, TH, RET, MAP2 and NPY." (PMID 25406647, 2014).
paraneoplastic cerebellar degeneration (1 paper, 2022). A rare, immune-mediated disorder characterized by cerebellar degeneration due to the presence of an often undetected malignancy (usually carcinoma or lymphoma) in an anatomic site other than the cerebellum. "DNER (delta/notch-like epidermal growth factor-related receptor) has been shown to be the antigen for the Tr-antibodies that are associated with Hodgkin lymphoma and paraneoplastic cerebellar degeneration." (PMID 35204019, 2022).
tophaceous gout (1 paper, 2023). "Nominally significant differences were observed for 7 proteins: TRAIL (TNF-related apoptosis-inducing ligand), DNER, IL-10, and CCL3 were reduced, and IL-6, RANKL (Receptor activator of nuclear factor kappa-Β ligand), and MCP-3 were elevated in samples of patients with tophaceous gout." (PMID 37810213, 2023).
Type 2 Diabetes (1 paper, 2023). "Genome-wide studies in two independent populations have implicated Delta/Notch-like EGF-related receptor (DNER) as a potential susceptibility loci for Type 2 diabetes in humans." (PMID 37223028, 2023).
cancer (12 papers, 2019 to 2024). A tumor composed of atypical neoplastic, often pleomorphic cells that invade other tissues. "Furthermore, DNER has also been implicated as an oncogene, as it promotes the proliferation, migration, and invasion of various cancer cells." (PMID 37373228, 2023). "In this study, we have revealed the previously unrecognized role of DNER in cancer progression, EMT and the apoptosis of BC cells." (PMID 32811806, 2020). "Most of the proteins were up-regulated in cancer patients although lower NPX levels were seen for two proteins, ITGAV and DNER, in cancer patients." (PMID 33075095, 2020). "Clearly, DNER appears to play a role in maintaining the proliferation and survival of cancer cells, which might therefore result in a poor prognosis for the cancer patient." (PMID 37373228, 2023). "Until now, the role of DNER in cancer has remained controversial, and the function of DNER may vary according to cell type." (PMID 32811806, 2020). "DNER is a neuron-specific transmembrane protein with extracellular EGF-like repeat sequences, which promotes the metastasis and proliferation of cancer cells by activating Girdin/PI3K/ATK signal transduction." (PMID 33462260, 2021).
tumor (12 papers, 2015 to 2025). "Delta/Notch-like epidermal growth factor (EGF)-related receptor (DNER) is a transmembrane protein involved in the development of tumours." (PMID 32811806, 2020). "Of these, DNER, a noncanonical Notch ligand implicated in promoting tumor growth, metastasis, and wound healing, was significantly reduced in LC participants, consistent with a prior study of plasma proteins in LC." (PMID 40924481, 2025). "DNER regulates its downstream target RBPJ and SKP1, and also interacts with the important factors of Wnt signaling pathways, CTNNB1 and CDH2, regulating tumor proliferation, differentiation, invasion, migration and angiogenesis of PanNENs tumorigenesis." (PMID 33329729, 2020). "We constructed a novel seven-gene signature (B3GALT5-AS1, DNER, CSN1S1, KIF5A, SIX3, NOTUM, and CPS1) and a combined prognostic model integrating a seven-gene signature with patient age and tumor size to quantify the likelihood of distant metastasis in lymph node-negative TNBC." (PMID 34604089, 2021). "However, only three genes/proteins, DNER, NT-3 and TIE2 showed the same direction of down-regulation in both plasma and tumor tissue." (PMID 29262574, 2017).
infection (3 papers, 2022 to 2025). The state of being infected such as from the introduction of a foreign agent such as serum, vaccine, antigenic substance or organism. "Next, patients with severe infection had a lower concentration of fifteen proteins among which TRANCE, DNER, and SCF were most significantly different." (PMID 36209073, 2022).
DNER also shares sentences with these, for which no sentence is quoted: glioblastoma (2 papers); acute GVHD (1); allergic rhinitis (1); Alzheimer disease (1); Arthritis (1); brain tumors (1); cerebellar ataxia (1); congenital heart disease (1); epilepsy (1); eye problems (1); glaucoma (1); hepatocellular carcinoma (1); kidney cancer (1); lung carcinoma (1); microcephaly (1); neurodevelopmental disorder (1); neurological diseases (1); osteoarthritis (1); paraneoplastic neurological syndromes (1); testicular cancer (1).